NNAT (neuronatin)
Diseases named in the same sentence as NNAT in open-access papers (continued):
Sharing a sentence is not in itself a finding about the gene and the disease.
osteosarcoma (2 papers, 2012 to 2020). A usually aggressive malignant bone-forming mesenchymal neoplasm, predominantly affecting adolescents and young adults. "Both MEST and NNAT are imprinted genes, and MEST has been shown to be down-regulated in a model of human osteosarcoma, suggesting a role in tumourigenesis." (PMID 23144859, 2012).
preeclampsia (2 papers, 2022 to 2025). Preeclampsia is a hypertensive disorder of pregnancy that is characterized by new-onset hypertension with proteinuria presenting after 20 weeks of gestation, and depending on mild or severe forms may initially present with severe headache, visual disturbances, and hyperreflexia. "DMR2 spans Bladder cancer-associated protein (BLCAP), a known differentially methylated gene in the placenta associated with preeclampsia, and the maternally imprinted Neuronatin (NNAT) locus has raised expression in the severely preeclamptic placenta." (PMID 41286963, 2025).
breast tumor (1 paper, 2023). "Elevated NNAT protein in ER + breast tumor biopsies was previously associated with decreased tumorigenic potential and prolonged patient survival, yet the underlying regulators of NNAT expression remain elusive." (PMID 37400769, 2023).
Cognitive impairment (1 paper, 2011). Abnormal cognition is characterized by deficits in thinking, reasoning, or remembering. "We posit therefore, that understanding the action and regulation of NNAT may shed light on the molecular basis of certain forms of cognitive impairment, particularly those associated with aberrant Ca2+ signaling." (PMID 21935485, 2011).
eating disorder (1 paper, 2023). A broad group of psychological disorders with abnormal eating behaviors leading to physiological effects from overeating or insufficient food intake. "The decreased Neuronatin expression in AN provides evidence that Neuronatin is implicated in the pathogenesis of eating disorders." (PMID 37630847, 2023).
embryonic neoplasms (1 paper, 2013). "Both loci were chosen due to the known overexpression of IGF2 and NNAT in embryonal tumors and their key role in embryonic development." (PMID 23825673, 2013). "Aberrant expression of imprinted genes, such as those coding for the insulin-like growth factor 2 (IGF2) and neuronatin (NNAT), is a characteristic of a variety of embryonic neoplasms, including Wilms tumor (WT)." (PMID 23825673, 2013).
insulinoma (1 paper, 2018). "Protein lysates from MIN6 cells, a mouse insulinoma-derived β cell line, were incubated with antibodies against endogenous NNAT, and the immunoprecipitate analyzed by mass spectrometry." (PMID 29864031, 2018).
neuroendocrine tumor (1 paper, 2023). "It has been reported that NHLRC1, an E3 ubiquitin protein ligase, mediates NNAT ubiquitination in PC12 neuroendocrine tumor cells." (PMID 36708951, 2023).
papillary thyroid cancer (1 paper, 2017). "We found a significant association between the localization of RET mutations and the expression of three genes: NNAT (suggested to be a tumour suppressor gene), CDC14B (involved in cell cycle control) and NTRK3 (tyrosine receptor kinase that undergoes rearrangement in papillary thyroid cancer)." (PMID 28181547, 2017).
sarcoma (1 paper, 2013). A usually aggressive malignant neoplasm of the soft tissue or bone. "The top markers for differentiation of sarcoma cluster 2 (LMS samples) and sarcoma cluster 5 (MLS samples) were SPEG (striated muscle preferentially expressed protein kinase) and NNAT (neuronatin), respectively." (PMID 24345474, 2013).
tumor (17 papers, 2008 to 2025). "MiR-708-5p is a circulating miR which acts as a tumor-suppressor by targeting an endoplasmic reticulum (ER) protein neuronatin (NNAT), causing a decrease in intracellular calcium." (PMID 33849540, 2021). "In our data, the overexpression of the NNAT gene was observed in tumours with MEN2A-like mutations." (PMID 28181547, 2017). "NNAT (Neuronatin) is an imprinted protein-coding gene thought to be involved in brain and pituitary development and maturation and, perhaps, tumor development." (PMID 40362297, 2025). "The present analysis suggests a tumor suppressor role for NNAT expression in human OS, potentially resulting from sensitization to ER stress-associated cytotoxicity." (PMID 32499872, 2020). "Specifically, two isoforms of the membrane proteolipid neuronatin (NNAT) were expressed exclusively within the tumor stem cells." (PMID 22624064, 2012). "Detailed analysis of the events downstream of Ca2+ release and the effect of NNAT expression, or lack thereof, on these cell-specific processes or properties will be necessary to facilitate a more mechanistic understanding of the roles of NNAT in tumor promotion versus tumor suppression." (PMID 32499872, 2020). "While Group 3 tumors mainly expressed photoreceptor markers, Group 4 tumor cells expressed mainly UBC markers, including EOMES, OTX2, NNAT, and LMX1A consistent with their proposed cells of origin." (PMID 39659836, 2024). "In comparison, stable overexpression of NNAT in T47D and ZR75 cells significantly increased basal cytoplasmic Ca2+ concentration, which coincided with significantly decreased tumor cell proliferation compared with control cells." (PMID 37400769, 2023). "Three (NNAT, SST and NPTX1) of the 7 hypermethylated gene promoters have been reported to be methylated in tumours previously." (PMID 19025626, 2008). "Notably, proliferation of T47D and ZR75 cells was not suppressed by overexpression of NNAT lacking the putative EndoR retention signal, suggesting that the tumor suppressive role(s) of NNAT function through the EndoR." (PMID 37400769, 2023). "Investigated molecules without connection to common key tumor proteins are GNAS, USP8, USP48, HHIPL1, NNAT, RHOU, C5orf66 and RASSF3, which seem to be more specific biomarkers and therefore should be validated for concordant differences in liquid biopsies." (PMID 32498309, 2020).
cancer (9 papers, 2015 to 2025). A tumor composed of atypical neoplastic, often pleomorphic cells that invade other tissues. "Many of these genes have previously been reported in cancer and also in the context of NB including NNAT, RB1, MAGEL2, GPR1, NDN." (PMID 39217334, 2024). "We explore the potential involvement of NNAT in Ca2+-ROS relationship as a major mechanism in cell apoptosis and cancer cell survival." (PMID 37400769, 2023). "Our data indicate that ROS-mediated NNAT expression strongly regulates cell cycle mechanisms and may control unchecked cell division in cancer." (PMID 37400769, 2023). "For example, the four imprinted regions on chromosome 20q (MCTS2, NNAT, L3MTBL1 and GNAS) were invariable subject to copy-number gains with very few deletions observed in the four cancer types." (PMID 28883545, 2017). "NNAT was recently linked to PPAR levels in adipocytes and was separately colocalized to the peroxisome in the pituitary cells; however, the cancer-specific role of NNAT in peroxisome mediated oxidative stress has not been evaluated." (PMID 37400769, 2023).
brain disorder (1 paper, 2023). A disease affecting the brain or part of the brain. "In the context of this mini-review, we have highlighted recent advances supporting the implication of prominent ER and cytosolic Ca2+ regulators (i.e., SERCA2, IP3Rs, RyRs, PVALB, NNAT) in the neurobiology of brain disorders with a strong neurodevelopmental component." (PMID 36875674, 2023).
cardiovascular diseases (1 paper, 2022). "TCF21, CDH19, XG, and NNAT might serve as feature genes for CAD, providing new insights for future research on the pathogenesis of cardiovascular diseases." (PMID 36345357, 2022). "In addition, the four feature genes identified (TCF21, CDH19, XG, and NNAT) might serve as feature genes for CAD, bringing new insights into the pathogenesis of cardiovascular diseases." (PMID 36345357, 2022).
neurodegenerative disease (1 paper, 2022). A disorder of the central nervous system characterized by gradual and progressive loss of neural tissue and neurologic function. "The second most significant DMR is located in the promoter region of the NNAT gene, which encodes the neuronatin protein that aggregates and causes cell death in another neurodegenerative disease called Lafora disease." (PMID 35982059, 2022).
NNAT also shares sentences with these, for which no sentence is quoted: glioma (2 papers); lung carcinoma (2); metabolic disease (2); anorexia nervosa (1); astrocytomas (1); bladder cancer (1); bone cancer (1); chylomicron retention disease (1); familial lipoprotein lipase deficiency (1); hyperglycaemia (1); Insulin resistance (1); large cell neuroendocrine carcinoma (1); leukemia (1); malignant peripheral nerve sheath tumor (1); megalencephalic leukoencephalopathy with subcortical cysts (1); neoplasms of eccrine (1); neuroblastoma (1); non-small cell lung carcinoma (1); renal carcinoma (1); schizophrenia (1); type 1 diabetes (1); type 2 diabetes (1); Wilms tumor (1).